CSF2 (colony stimulating factor 2)
Diseases named in the same sentence as CSF2 in open-access papers (continued):
Sharing a sentence is not in itself a finding about the gene and the disease.
rheumatoid arthritis (121 papers, 2006 to 2025). A chronic, systemic autoimmune disorder characterized by inflammation in the synovial membranes and articular surfaces. "CSF2 is a pro-inflammatory cytokine implicated in many diseases, including diabetes, rheumatoid arthritis and cancer, through its links to other pro-inflammatory cytokine such as tumor necrosis factor (TNF) and IL-1." (PMID 29206834, 2017). "Pathogenic Th17 cell, as a special Th17 cell subset, triggered and aggravated the immune response of chronic inflammatory diseases, such as periodontitis, IBD, and rheumatoid arthritis, through IL-17, IL-21, IL-22, IL-23, and GM-CSF (gene: CSF2)." (PMID 41318555, 2025). "CSF2 is a key cytokine known to enhance progression of autoimmune inflammatory diseases such as rheumatoid arthritis and crescentic glomerulonephritis." (PMID 39005931, 2024). "CSF2 has pro-inflammatory effects and is involved in the pathogenesis of various diseases, such as rheumatoid arthritis, cancer, and metabolic diseases." (PMID 38238696, 2024). "Studies have shown that CSF2 is highly expressed in joints with rheumatoid arthritis, and inflammation and injury can be reduced by blocking CSF2." (PMID 31673142, 2019). "A high level of Csf2 is detected in joints with rheumatoid arthritis, while an increase in Csf2-expressing B cells is detected in patients with multiple sclerosis." (PMID 27164082, 2016). "Recently, Csf2 has been revealed as a potential therapeutic target in rheumatoid arthritis as well as multiple sclerosis, an inflammatory demyelinating disease in the central nervous system." (PMID 27164082, 2016). "HS exerted treatment effects on RA by regulating 4 core targets (CSF2, IL1β, TNF, and IL6), which involved in 15 pathways such as rheumatoid arthritis, TNF signaling pathway, and cytokine-cytokine receptor interaction." (PMID 31885670, 2019). "As with the original DMG-alone analysis, the MEGs were also significantly 3.75-fold enriched in the KEGG ‘Rheumatoid arthritis‘ pathway (q = 1.70E-02, where q is a multiple-test corrected P-value) with 7 out of 89 genes: ANGPT1, CSF2, CTLA4, HLA-DQA1, HLA-DQA2, HLA-DRA and HLA-DRB1." (PMID 25901943, 2015).
pulmonary alveolar proteinosis (115 papers, 2005 to 2026). A rare lung disorder characterized by the filling of the pulmonary alveoli with proteinaceous material which stains positive with periodic acid-Schiff stain. "According to the current understanding, Csf2- and Csf2rb-deficient mice develop pulmonary alveolar proteinosis (PAP) due to a defect in terminal maturation of AM involving impaired lipid catabolism." (PMID 24699679, 2014). "Disruption of CSF2 resulted in pulmonary alveolar proteinosis due to compromise in the development of alveolar macrophage, making lungs susceptible to infection." (PMID 33362771, 2020). "In mice with homozygous humanization of the Csf2 locus, the absence of mouse GM-CSF induces alveolar macrophage deficiency in the lung and a resulting pathology described as pulmonary alveolar proteinosis, recapitulating the phenotype of Csf2 knockout mice." (PMID 33692812, 2021). "Irradiated WT recipients that received BM from either Csf2−/− or WT mice did not develop any pulmonary alveolar proteinosis during 16 weeks post-reconstitution." (PMID 24699679, 2014).
neutropenia (106 papers, 1990 to 2025). A decrease in the number of neutrophils found in the blood. "Granulocyte-macrophage colony-stimulating factor (CSF) (also known as CSF2) and granulocyte-CSF (also known as CSF3, G-CSF) are important survival and proliferation factors for neutrophils and macrophages, and deficiency of CSF3 leads to neutropenia." (PMID 38745657, 2024). "In this context, it is sobering to rethink the adjuvant administration of recombinant CSF2 to ameliorate therapy-induced neutropenia in CSF2-releasing cancers 49, such as myxofibrosarcomas with overexpressed and activated PAK1, which is at risk of detrimental cancer-promoting effect." (PMID 37564209, 2023).
colitis (100 papers, 2007 to 2026). Inflammation of the colon. "In particular, the enhanced secretion of IFN-γ, CSF2, and IL-17 by ILC3s is detrimental in various colitis mouse models." (PMID 34341503, 2021). "Similarly, in colon tissue from a human with active colitis, EPICERTIN significantly upregulated CSF2 and tissue repair-associated genes while downregulating proinflammatory genes (IL1B, IL6ST)." (PMID 41651223, 2026). "The therapeutic effect on endoscopic signs of colitis was accompanied by diminished expression levels of proinflammatory mediators within colon tissues as we detected reduced amounts of Il1b, Tnf, Csf2, and Ifng transcripts in anti-IL-7R/anti-GM-CSF- compared to control antibody-treated mice." (PMID 29910804, 2018).
prostate carcinoma (94 papers, 2001 to 2026). A carcinoma that arises from epithelial cells of the prostate gland. "Among CHD1 target genes, immediate early response 3 (IER3), leukemia inhibitory factor (LIF), and colony stimulating factor 2 (CSF2) were significantly correlated with ESS2 expression in patients with prostate cancer." (PMID 37524814, 2023). "In the context of prostate cancer, BHLHE22 and PRMT5 assemble a transcriptional complex that initiates CSF2 transcription, which then attracts many immunosuppressive neutrophils and monocytes, promoting the tumor’s metastasis to the bones." (PMID 40242775, 2025). "RNA sequencing data shows an upregulation of immunogenic chemokines and cytokines (CXCL, CSF2, IL6, and TNF) in human prostate cancer cells (PC3, PC3M) and Luminex-assayed cytokine response in mice treated with CRC2631." (PMID 33216833, 2020).
Arthritis (84 papers, 2006 to 2025). Inflammation of a joint. "In contrast to these results, we did not observe any significant differences regarding the severity of arthritis, including articular Csf2 mRNA levels, in IL-18-deficient as compared to WT mice." (PMID 37415987, 2023). "The affected 5q LOH interval harbors several cytokine genes (including IL-3, IL-4, IL-5, IL-13, and CSF2), a gene associated with arthritis susceptibility (SLC22A4), a DNA repair gene (RAD50), and a gene that promotes Type 1 interferon responses (IRF1)." (PMID 25107306, 2014). "To further assess the possible contribution of GM-CSF from non-CD4 T cells to arthritis development, we transferred Csf2−/− or WT SKG CD4+ T cells into Rag2−/− or Csf2−/−Rag2−/− mice." (PMID 29802020, 2018). "Transfer of Csf2−/− SKG CD4+ T cells induced histologically evident arthritis in Rag2−/− mice although the arthritis was macroscopically less severe than WT SKG CD4+ T cell transfer." (PMID 29802020, 2018). "We found here that systemically administered IL-23 could elicit pain and arthritis in a mBSA-injected joint and that neutralization of TNF and deletion of Csf2 and Ccl17 prevented the pain and reduced the associated arthritis." (PMID 39107827, 2024). "Csf2−/− SKG CD4+ T cells were able to induce autoimmune arthritis in all the recipient mice, although arthritis was significantly less severe than that induced by WT SKG CD4+ T cell transfer." (PMID 29802020, 2018). "In accordance with the absence of difference in arthritis severity, Csf2 mRNA levels were comparable in IL-18 KO mice and WT littermates." (PMID 37415987, 2023). "In contrast, not only Csf2−/− SKG CD4+ T cells but also WT SKG CD4+ T cells completely failed to induce arthritis macroscopically and histologically in Csf2−/−Rag2−/− mice." (PMID 29802020, 2018). "In addition, Csf2−/− SKG mice completely failed to develop arthritis regardless of the presence of effector Th17 cells in the periphery, indicating an indispensable role of GM-CSF in SKG arthritis." (PMID 31497022, 2019). "Thus, the failure in arthritis development following transfer of CD4+ T cells into Csf2−/− hosts could be attributed not to impaired Th17 cell differentiation but to impaired GM-CSF production by certain host non-T cells stimulated by Th17 cells." (PMID 29802020, 2018).
colorectal cancer (81 papers, 2008 to 2025). A primary or metastatic malignant neoplasm that affects the colon or rectum. "In addition, the s-CSF2-Ab levels were associated with unfavorable postoperative prognosis in colorectal cancer (CRC)." (PMID 36844744, 2023). "Building upon its reported pro-tumorigenic functions in gastric and colorectal cancers, this study selected CSF2 as a focal gene for investigation." (PMID 41216204, 2025). "Fourth, we found that NCTD promoted macrophage M1 polarization not only directly through increasing CSF2 but also by inducing colorectal cancer cells to secrete CSF2." (PMID 40394236, 2025). "KRAS-mutant tumors were shown to reprogram macrophages to promote therapeutic resistance and malignant progression by driving the production of CSF2 and lactate in colorectal carcinoma." (PMID 38618956, 2024). "CSF-2 (GM-CSF) upregulation has been observed in F. nucleatum-infected gingiva-derived mesenchymal stem cells, and a role for CSF-2 in the colorectal cancer epithelial-to-mesenchymal transition has been proposed." (PMID 34700376, 2021). "Furthermore, CSF2 has been shown to exert antitumor activity in gastrointestinal tract cancers, such as esophageal cancer (EC; 13), colorectal cancer (CRC), and gastric cancer (GC; 15)." (PMID 36844744, 2023).
lung carcinoma (80 papers, 1994 to 2025). "Analysis using this lung cancer model in Csf2-KO mice also indicated that the tumor size was smaller in the absence of AMs." (PMID 38720352, 2024). "Our discoveries highlight that the CSF2/lnc‐CSRNP3 relationship could be a new target for treatment to overcome osimertinib resistance in lung cancer patients." (PMID 39036343, 2024). "For example, serum CSF2 level has been demonstrated to be increased in patients with lung cancer, and CSF2‐dependent activation of the JAK2/signal transducer and activator of transcription 3 (STAT3) pathway is important in tumor angiogenesis and vascularization." (PMID 39036343, 2024). "In summary, the current study demonstrates that Spi-B-positive lung cancer cells play an important role in increasing TAM recruitment by upregulating the expression of various cytokines, such as CSF2, IL6, CCL3, and CCL4." (PMID 34141615, 2021). "Furthermore, CSF2-cFLiMo can overcome the limitation in macrophage precursor numbers and be used as a therapeutic approach for PAP disease or in other macrophage-based cell therapies, including lung emphysema, lung fibrosis, lung infectious disease, and lung cancer." (PMID 35393945, 2022).
viral infection (74 papers, 2007 to 2026). "Csf2-/- mice are susceptible to several intracellular bacterial and viral infections in the lung, but a role for GM-CSF in CD4 T cell-mediated immunity to Chlamydia is yet to be established." (PMID 38271477, 2024). "Some genes, such as CSF2, were not differentially regulated in HAlone, but the combination of hypoxia and viral infection resulted in a significantly higher level of CSF2 mRNA compared to NOC43 (160-fold in NOC43 compared to 7920-fold in HOC43, padj = 1.60 × 10−5)." (PMID 40867589, 2025). "Among the pro-inflammatory mediators, a significant increase in mRNA for CSF2, CSF3, CXCL2, CXCL5, IL6, IL8, and also IL1 and IL18 was observed 24 h after viral infection." (PMID 23723976, 2013).
leukemia (70 papers, 2002 to 2026). A malignant (clonal) hematologic disorder, involving hematopoietic stem cells and characterized by the presence of primitive or atypical myeloid or lymphoid cells in the bone marrow and the blood. "Colony stimulating factor 2 (CSF2) encodes a protein that helps control differentiation, and CSF2 is localized in chromosome 5q31, which is known to be associated with leukemia (RefSeq: NG_033024.1)." (PMID 32649728, 2020). "After GO analysis of the seventy-four genes, six secreted cytokines related to cell cycle, proliferation and apoptosis including CSF2, CTF1, FGF2, IGF2, HGF and LIF were selected for PCR verification and FGF2 was confirmed to be significantly up-regulated in leukaemia mice derived MSCs." (PMID 36333298, 2022).
multiple sclerosis (70 papers, 2012 to 2025). A progressive autoimmune disorder affecting the central nervous system resulting in demyelination. "Consistently, the expression of inflammatory cytokines such as IL-8 and TNF-α in diabetic patients and IL-6, IL-8, CSF2 and TNF-α in multiple sclerosis patients increased." (PMID 31294790, 2019).
influenza (69 papers, 2008 to 2025). An acute viral infection of the respiratory tract, occurring in isolated cases, in epidemics, or in pandemics; it is caused by serologically different strains of viruses (influenzaviruses) designated A, B, and C, has a 3-day incubation period, and usually lasts for 3 to 10 days. "Transplanted CSF2-cFLiMo more efficiently engrafted empty alveolar macrophage niches and protected mice from influenza infection compared with transplanted BM cells cultured with M-CSF (CSF1-cBMM) or CSF1/CSF2-cBMM." (PMID 35393945, 2022). "Upon influenza infection, Csf2ra–/– mice containing CSF1-cBMM–derived alveolar macrophages showed strikingly increased morbidity (i.e., loss of body weight and temperature; O2 saturation) and mortality compared with mice containing CSF2-cFLiMo–derived alveolar macrophages." (PMID 35393945, 2022). "Next, we reconstituted Csf2ra–/– mice with CSF2-cFLiMo or CSF1-cBMM to compare their ability to ameliorate influenza-induced morbidity." (PMID 35393945, 2022). "A specific role for GM-CSF (CSF-2) has also been identified, with concentrations in the blood increasing with disease severity, in contrast to influenza where no elevation is observed." (PMID 35686910, 2022).
Autoimmunity (67 papers, 2004 to 2025). The occurrence of an immune reaction against the organism's own cells or tissues. "Given the positive regulation of proinflammatory genes (e.g., IL17, CXCL13, and CSF2) by MIAT, we were interested in investigating the significance of MIAT in autoimmunity." (PMID 35784351, 2022).
ovarian carcinoma (60 papers, 1991 to 2025). A malignant neoplasm originating from the surface ovarian epithelium. "It is reported that MDSCs activate STAT3 signaling by stimulating the expression of colony stimulating factor 2 (CSF2) in epithelial ovarian cancer, thereby enhancing the transcription of SOX2, NANOG, OCT4a, C-MYC, and KLF4, as well as cancer stemness." (PMID 38561775, 2024). "Additionally, myeloid-derived suppressor cells have been found to enhance the stemness of epithelial ovarian cancer cells through activation of the CSF2/p-STAT3 signaling pathway." (PMID 37865637, 2023). "For example, with CSF-2 (known as granulocyte-macrophage colony-stimulating factor, GM-CSF), knock-out mice show reduced neutrophil function, and CSF-1 (known as macrophage colony-stimulating factor, M-CSF) has been observed to increase the Th1/Th2 ratio in ovarian cancer patients." (PMID 38612319, 2024). "In epithelial ovarian cancer (EOC), MDSC is reported to promote EOC cell stemness, which is achieved by activating colony-stimulating factor 2 (CSF2)/p-STAT3 signaling in EOC cells co-cultured with MDSC." (PMID 34689842, 2021). "In addition to its suppressive activity against CD8+ T cells in ovarian cancer TME, previous studies have demonstrated that MDSC increase the stem cell-like properties of ovarian cancer cells via by producing PGE2, inducing the microRNA101 or CSF2/STAT3 pathway activation." (PMID 33562495, 2021).
colon carcinoma (59 papers, 1990 to 2025). "In AOM/DSS-induced and T-bet−/−, Rag2−/− CAC models, IL-6, CCL2, G-CSF, and GM-CSF (encoded by Csf2) fostered MDSC accumulation in evolving colonic tumors and boosted T cell suppression by MDSCs in a STAT-dependent manner." (PMID 40244120, 2025).
atherosclerosis (58 papers, 2009 to 2025). A disease characterized by the build-up of fatty material and calcium deposition in the arterial wall resulting in partial or complete occlusion of the arterial lumen. "The observed correlation with max-IMT suggested that s-CSF2-Ab levels were associated with early atherosclerosis prior to stenosis." (PMID 36844744, 2023). "In the present study, we found that the s-CSF2-Ab levels were significantly associated with hypertension, which is a major risk factor for not only atherosclerosis but also AIS and AMI." (PMID 36844744, 2023). "Preclinical studies consider colony-stimulating factor 2 (CSF2) as an essential cytokine with a causal relationship to atherosclerosis and cancer." (PMID 36844744, 2023). "Granulocyte macrophage colony-stimulating factor (GM-CSF, Csf2) is a growth factor for myeloid-lineage cells that has been implicated in the pathogenesis of atherosclerosis and other chronic inflammatory diseases." (PMID 32012959, 2020). "Thus, s-CSF2-Ab might have a causal relationship with the development of atherosclerosis and cancer." (PMID 36844744, 2023). "Results of this study suggest that the measurement of serum s-CSF2-Ab levels can provide valuable information for diagnosing atherosclerosis-related AIS and solid cancers." (PMID 36844744, 2023). "CSF2 has been demonstrated to have a protective impact on atherogenesis, and the administration of CSF2 has been reported to prevent the progression of atherosclerosis via changes in the composition of atherosclerotic lesions." (PMID 36844744, 2023). "Taken together, these results indicate s-CSF2-Ab as a potentially valuable therapeutic target for the prevention of atherosclerosis and solid cancers." (PMID 36844744, 2023). "This may explain the overall higher positive rate of s-CSF2-Ab in patients with solid cancer than those in patients with atherosclerosis-related AIS, AMI, DM, and CKD." (PMID 36844744, 2023). "The administration of CSF2 has been demonstrated to prevent the progression of atherosclerosis." (PMID 36844744, 2023). "We examined the serum anti-CSF2 antibody levels in patients with atherosclerosis or solid cancer." (PMID 36844744, 2023). "The s-CSF2-Ab levels were closely correlated with max-IMT, plaque score, and cardio-ankle vascular index, which are typical indices of atherosclerosis leading to AIS and AMI." (PMID 36844744, 2023). "In addition, they demonstrated that CB-ECFCs were able to decrease the expression of mediators of inflammation and atherosclerosis produced by allogeneic lymphocytes and monocytes (IL-1β, IL-8, PGF, ALOX-5, TNFα, CSF-2, MMP-1, MMP-9) more significantly than adult ECFCs." (PMID 32381102, 2020).
atherosclerosis (continued). "Because detailed statistics on medications taken by patients prior to hospital admission are not available, we were unable to study the specific effects of drugs on s-CSF2-Ab levels, and further studies are needed in patients who were not taking drugs that could affect atherosclerosis and cancer." (PMID 36844744, 2023).